INS (insulin)
Diseases named in the same sentence as INS in open-access papers (continued):
Sharing a sentence is not in itself a finding about the gene and the disease.
depression (continued). "Coexisting CAT, polyneuropathy, depression, and the use of insulin pumps were significant risk factors for FSD." (PMID 33117456, 2020). "A total of 282 males (n =112) and females (n = 170) with T1D (18–79 years) participated.Overall, psychological aspects (i.e. illness perceptions, coping strategies,insulin beliefs, anxiety, and depression) were associated with EDpsychopathology." (PMID 33282331, 2020). "There have been experiments showing that major depression is associated with glucose/insulin metabolism." (PMID 32281722, 2020). "This study showed that children’s sleep issues and behavioural insomnia associates with increased parental stress, anxiety, and depression symptoms, influencing the intensive insulin regimen." (PMID 33379307, 2020). "Consistently, insulin administration improves working memory in both human and animal studies, confirming that insulin is involved in hippocampal neurogenesis linked with depression." (PMID 33568996, 2020). "Enrichment of Lactobacillus is associated with lowering Beck Depression Inventory scores, serum insulin level, serum high-sensitivity C-reactive protein, and biomarkers of oxidative stress in patients with major depressive disorder (MDD)." (PMID 32882999, 2020). "This association between insulin therapy and depression has been observed in other studies done in Republic of Korea and China." (PMID 30775378, 2019). "Factors independently associated with a diagnosis of mild to moderate depression were being on insulin therapy and being a current smoker." (PMID 30775378, 2019). "In this study depression was significantly associated with being a current smoker and being on insulin therapy." (PMID 30775378, 2019). "Being a current smoker and being on insulin therapy were strongly associated with having mild to moderate depression." (PMID 30775378, 2019). "This is probably because the depressive systems are mainly correlated with impaired insulin sensitivity or low insulin secretion, and the risk of depression gradually increases along with the deterioration of glucose metabolism." (PMID 30233306, 2018). "Mendelian randomization analyses suggested variants associated with body mass index, fasting insulin, menopause timing, depression and male-pattern balding play a causal role in PCOS." (PMID 30566500, 2018). "The decreased secretion and sensitivity level of insulin, another common hypoglycemic hormone, appears to be a risk factor for depression." (PMID 30233306, 2018). "Female gender, being unmarried, frequent intake of alcohol, previous smoking status and insulin use were associated with increased odds of depression, whereas being educated above basic school level was associated with a decreased odds of depression." (PMID 30400843, 2018). "Mendelian randomization suggested that there was a causal role for BMI, fasting insulin and depression pathways." (PMID 30566500, 2018). "Increased KYN and its derivatives play a role in depression, age-associated chronic inflammation and reduced insulin activity." (PMID 27809283, 2016). "Evidence of the impact of PA on stroke; CHD; CVD; bone mineral density; insulin sensitivity; and risk of anxiety and/or depression." (PMID 26845035, 2016). "Hypercortisolemia is a likely mechanism underlying the observed depression-central obesity synergy, as cortisol can interfere in glucose regulation by altering both insulin secretion and insulin sensitivity." (PMID 27755576, 2016). "Cortisol and catecholamines are also increased with mental stress and depression causes inactivity, which combine with increased cortisol levels, increased adiposity and insulin resistance." (PMID 26552427, 2015). "The role of insulin secretion is more obscure, though a longitudinal study found that low insulin secretion is a risk factor for depression in middle-aged women." (PMID 26199013, 2015).
depression (continued). "It is possible that there is a relation between depression and insulin initiation, but only when certain depression characteristics are present, e.g. fatigue or loss of energy, low self-esteem and/or diminished ability to think, concentrate or make decisions." (PMID 24223860, 2013). "For none of the candidate confounders, adjustment produced a statistically significant association between depression and time to insulin initiation." (PMID 24223860, 2013). "Percent change in the regression coefficient for depression in the association with time to insulin initiation, after adjustment for potential confounders." (PMID 24223860, 2013). "Low-educated people were more likely to develop depression than educated people (OR=3.09) and being on insulin treatment also had a significant association with depression (OR=3.31)." (PMID 23961989, 2013). "The unbiased inclusion of additional nodes significantly linked to depression-affected genes identified insulin–a recurrently-suggested contributor to neuropsychiatric disorders - as a putative modulator for both networks." (PMID 20376317, 2010). "The Brain-Pancreas Relative Protein (BPRP) was reported to induce depression and its loss resulted in decrease blood level of insulin leading to increase blood glucose level in CMS model." (PMID 18435835, 2008). "When categorized by pharmacotherapeutic class of antidiabetic medications, poor health related quality of life (OR: 0.97, 95%CI: 0.95–0.99) was associated with higher risk of depression in patients on insulin therapy." (PMID 17683531, 2007). "Poor health related quality of life (OR: 0.97, 95%CI: 0.95–0.99) was associated with higher risk of depression in patients on insulin therapy." (PMID 17683531, 2007). "Among the patients on insulin therapy and/or combination therapy, higher odds of depression were associated with lower HRQoL as measured by SF-12 instrument." (PMID 17683531, 2007). "Lower depression risk was associated with exposure to metformin (0.61[0.57-0.66]) compared with no antidiabetes agents, and to pioglitazone (0.25[0.10-0.63]), linagliptin (0.26[0.13-0.52]), and insulin (0.63[0.55-0.72])." (PMID 42253148, 2026). "The protective role of insulin pumps against elevated distress (RR = 0.938) is supported by recent Saudi data associating pump use with lower odds of severe depression (OR = 0.38) and anxiety (OR = 0.42), particularly among females and those with better glycemic control." (PMID 41517010, 2025). "We start by discussing the causal route from metabolic disruption to depression (e.g., disruptions in insulin signaling altering mental health), before exploring reverse causality (e.g., depression increases behavior that confers risk for metabolic ill-health)." (PMID 40991698, 2025). "We also evaluated the use of anti-depressants in our patient population as diagnosis of depression is associated with higher A1c levels and patients with depression are more likely to skip insulin, which could increase risk of DKA." (PMID 40940823, 2025). "Improvements in metabolic health and insulin sensitivity from RT may further relieve depressive symptoms, as metabolic dysregulation has been implicated in depression pathophysiology." (PMID 41473524, 2025). "These factors may affect both metabolic indicators and depression risk, for example, sleep disorders may contribute to both insulin resistance and affect mood regulation." (PMID 40672420, 2025). "It is also reported that the insulin insensitivity caused by pro-inflammatory cytokines may result in metabolic abnormalities that are associated with depression." (PMID 38398483, 2024). "This was a cross-sectional study, implying that the associations of insulin treatment strategies, regular physical activity, and social support with comorbid depression might be bidirectional." (PMID 36918821, 2023).
depression (continued). "Participants undergoing insulin treatment have a higher risk of comorbid depression, and those with regular physical activity or higher social support were at a lower risk of comorbid depression." (PMID 36918821, 2023). "On the other hand, a higher intake of monounsaturated fatty acids (MUFAs) may promote insulin signaling in the brain and preserve the integrity of the brain's dopamine system, consequently diminishing the risk of depression." (PMID 36909144, 2023). "However, males, older age, participants with alcohol-related disorders, chronic kidney disease, COPD, depression, higher numbers of oral antidiabetic drugs, insulin, and aspirin use had a significantly higher risk of hospitalization for all-cause pneumonia." (PMID 36876083, 2023). "The association between T1D and DEB could be attributed to the presence of several risk factors for DEB in T1D, like lifelong insulin therapy, attendant weight gain, food preoccupation (e.g., carbohydrate counting), low self‐esteem, and depression." (PMID 35379350, 2022). "For example, the activation of sympathetic nervous system and increases in cortisol and catecholamine levels as a result of depression could cause changes in insulin resistance and glycaemic function, both of which can increase DR risk." (PMID 36494641, 2022). "Additionally, to this result, we found a positive association between depression severity and the change of insulin during an ECT series." (PMID 35212862, 2022). "Diabetic complications, insulin use and educational status have been identified as risk factors for co-morbid depression in patients with type 2 diabetes, whereas regular exercising, gender, marital status and current social status were demonstrated to be protective factors." (PMID 35253006, 2022). "Disrupted insulin sensitivity from mid-childhood appeared to be associated with adult psychosis, and BMI increases starting around the time of puberty onset were associated with adult depression." (PMID 33439216, 2021). "Thus, elevated cortisol concentrations were linked to insulin resistance and visceral adiposity, as well as psychological disorders such as depression and anxiety." (PMID 33805221, 2021). "This timely review analyzes the results of the association between insulin and depression may promote the development of this field and laying foundation for future research." (PMID 34366917, 2021). "Such inflammatory mediators interact with insulin, leading to insulin insensitivity and hypercortisolemia, can contribute to desensitisation of glucocorticoid receptors; all of these have been implicated in the aetiology of depression." (PMID 33467657, 2021). "Also, diabetics treated by both insulin and oral hypoglycemic drugs were six times more at risk of depression than those on oral hypoglycemic drugs only." (PMID 32637427, 2020). "HPA axis dysfunction is associated with insulin action in patients with depression." (PMID 33256267, 2020). "The insulin signalling pathway mediates the symptoms of depression caused by GC disorders." (PMID 32281722, 2020). "Consequently, a growing body of evidence has suggested that altered insulin signaling, including insulin availability and/or sensitivity or availability of insulin receptors, is important to the underlying pathophysiology of depression." (PMID 32971941, 2020). "BMI (OR = 1.13; 95 % C.I., 1.05−1.22), HOMA2 (OR = 1.12; 95 % C.I., 1.01−1.26), triglycerides (OR = 2.09; 95 % C.I., 1.35−3.24) and fasting insulin (OR = 1.42; 95 % C.I., 1.01-2.12) were associated with current depression with raised CRP, after adjusting for potential confounders." (PMID 32339985, 2020). "As discussed in the Introduction, some researchers have suggested that women with PCOS appear to have a unique risk for depression that is persistent over time, which could either be related to the condition itself, or to: weight, androgens, insulin, cortisol." (PMID 32479544, 2020).
depression (continued). "The researchers postulated that coffee may reduce mortality risk by affecting inflammation, lung function, insulin sensitivity, and depression." (PMID 30925782, 2019). "In unadjusted logistic regression models, being female (OR = 2.84), unmarried (OR = 1.63), regular alcohol consumer (OR = 5.47), former smoker (OR = 1.28), using insulin (OR = 1.3) and having poor glycaemic control (OR = 1.82) were associated with an increased odds of depression." (PMID 30400843, 2018). "Depression has been associated with poorer adherence to self-care regimens or insulin overdosing." (PMID 25984373, 2015). "Besides, the depression symptoms was also significantly associated with poorer glycemic control, the level of HbA1c, high fasting insulin values, 2-h glucose concentrations and insulin resistance." (PMID 26167205, 2015). "In logistic regression, apart from young age, poor education, long disease duration, tobacco use, high body mass index, use of insulin, depression was independently associated with failure to attain HbA1c target (Odds Ratio [OR] = 1.56, 95%CI:1.05–2.32, P = 0.028)." (PMID 25349949, 2015). "In the univariable Cox regression analysis, unadjusted confounding could have obscured the association between depression and time to insulin initiation." (PMID 24223860, 2013). "Whether there only is a relation with a later start of insulin therapy in those people for whom the motivational aspects of depression cause a general reluctance to start insulin, is yet to be determined in a prospective study." (PMID 24223860, 2013). "However, due to the increased statistical power of the current study, one cannot exclude that the difference in physiological insulin secretion observed is reflecting an underlying trait of depression associated with impaired glycemic control." (PMID 20161799, 2010). "Many patients dislike frequent insulin injections and self-monitoring blood glucose, which many clinicians recommend for such intensive insulin therapy, is associated with increased scores of depression and lower quality of life scores." (PMID 19143853, 2008). "Furthermore, pancreatic insulin secretion and neuronal activity showed opposite diurnal patterns, in which the Syt7-deficiency-induced disequilibrium induced periodic antagonistic shifts in the mania- and depression-like behaviors." (PMID 40330888, 2025). "However, a significant association between depression and insulin use was found even in patients with good GC (p < 0.001), regardless of whether HbA1c was high." (PMID 40429455, 2025). "Indeed, those patients requiring insulin had a 2.37 times higher risk of suffering from depression." (PMID 37237354, 2023). "Thus, InsRs on striatal astrocytes play a key role in the regulation of mood by insulin, which could contribute to increased susceptibility to depression in insulin-resistant conditions." (PMID 36979453, 2023). "Moreover, high intakes of starch and sugars and subsequent insulin secretion could increase the levels of circulating inflammatory markers, which may be associated with the risk of depression." (PMID 35745131, 2022). "However, management of GDM with insulin may be an indicator of its severity and four of the included studies compared risk for depression between different treatment modalities." (PMID 31693201, 2020). "Deficiencies in IR activation, insulin availability, and downstream IR-related mechanisms may result in aberrant IR-mediated functions and, subsequently, a broad range of brain disorders, including depression." (PMID 32971941, 2020). "The changes observed here, may thus explain some of the potential health and longevity benefits from fasting, with decreased levels of proline and tyrosine being associated with diminished symptoms of depression, lower resistance to insulin, and improved cognitive function." (PMID 30678028, 2019).
depression (continued). "To date, a number offactors have been proposed to cause diet-induced damage to the brain, includingoxidative stress, insulin resistance, inflammation, and changes invascularization, as all these factors can be modified by dietary intake and havebeen associated with occurrence of depression." (PMID 30254236, 2019). "In a similar vein, by only examining the role of baseline HbA1c levels, we might have missed clinically relevant changes in average blood glucose levels during follow-up that could have shed more light on the association between depression and insulin initiation." (PMID 24223860, 2013). "CGM was associated with improved psychosocial health in patients with T2D using insulin; therefore, it seems reasonable to deduce that patients with mental health impairment, such as depression or anxiety, would benefit from CGM use." (PMID 41601933, 2026). "No significant improvements were observed in sleep quality, menopausal symptoms, anxiety, depression, sexual function, BMI, or insulin levels." (PMID 41693954, 2026). "For example, A Korean study showed combined therapy patients had the highest depression rates (OR = 1.41), higher than insulin-only or oral-only users." (PMID 41189617, 2025). "Levels of neurotransmitters such as serotonin, dopamine and norepinephrine are altered in patients with depression, impairing neurotransmission and affecting glucose metabolism and insulin sensitivity." (PMID 40658313, 2025). "Cross-sectional and longitudinal data were used to disentangle the contributions of insulin resistance and inflammation to somatic and cognitive-affective symptoms of depression." (PMID 39951058, 2025). "Sedentary behavior correlates with lower well-being and quality of life, increased adiposity, higher levels of depression, and poorer laboratory parameters such as glucose, insulin, cholesterol, and triglycerides." (PMID 40150586, 2025). "Consistent with extensive evidence from prospective cohort studies worldwide, regular exercise improves cardiovascular function, controls weight, enhances insulin sensitivity, and alleviates anxiety and depression." (PMID 41323611, 2025). "The proportion of patients receiving basal plus bolus insulin was lower in the normal, mild, and moderate depression groups compared to the severe depression group." (PMID 40429455, 2025). "↓ insulin and insulin-like growth factor-II, ↓ BMIadditional benefits such as improved quality of life, social well-being, and reduced depression and anxiety (as assessed by validated questionnaires)." (PMID 40507486, 2025). "Insulin sensitivity improvements reduce inflammation, a key factor in psychiatric disorders such as depression and schizophrenia." (PMID 40365004, 2025). "HbA1c and intensive insulin treatment were the strongest predictors in the presence of both depression and T2DM." (PMID 40429455, 2025). "Preclinical models demonstrate that chronic stress and hypercortisolism in depression impair insulin signaling through glucocorticoid receptor-mediated suppression of IRS-1 phosphorylation." (PMID 40904459, 2025). "In contrast, the highly processed DP was rich in high-sugar, high-fat, and low-fiber foods, which can easily lead to physiological reactions closely related to depression, such as blood glucose fluctuations, insulin resistance, and chronic inflammation." (PMID 41164838, 2025). "It was seen that the mixed insulin ratio of groups with moderate and severe depression was higher than the groups with normal or mild depression (p < 0.05)." (PMID 40429455, 2025). "The most relevant predictive variables were potassium (K), folic acid, alkaline phosphatase, height, transferrin, body weight, BMI, triglyceride (Tg), Beck depression inventory score, and insulin." (PMID 40284254, 2025). "Depression exacerbates systemic inflammation, further impairing glucose metabolism and insulin sensitivity." (PMID 40218134, 2025).